CBX8 (chromobox 8)
Diseases named in the same sentence as CBX8 in open-access papers (continued):
Sharing a sentence is not in itself a finding about the gene and the disease.
cancer (36 papers, 2010 to 2025). A tumor composed of atypical neoplastic, often pleomorphic cells that invade other tissues. "CBX8 upregulation in LUAD has been associated with increased cancer cell invasion and migration, likely through pathways involving WNK2 and MMP2, which promote metastasis in 8- to 10-week-old NSG mice." (PMID 40175347, 2025). "Our investigation implied that CBX8 was positively or negatively linked to different immune cells in three cancers, indicating the potential immunotherapy approaches to cure these diseases." (PMID 35813444, 2022). "Many studies have implied that CBX8 is highly associated with malignant tumor occurrence and development, but its relationship with LIHC, KIRC, and OV and supporting regulatory mechanisms remains elusive." (PMID 35813444, 2022). "Finally, TCGA analysis showed that CBX8 level was correlated with a couple of pluripotency-associated genes, supporting its association with cancer stemness." (PMID 35681547, 2022). "Using current NAT criteria, a prognostic role for high levels of the cancer stemness-related gene and protein, chromobox 8 (CBX8) in NAT (worse DFS and OS) has been demonstrated." (PMID 39518025, 2024). "CBX8, encoding one subunit of PRC1 and involved in cancer and immune cell infiltration, is presented to show the elevated H3K4me3 and H3K27ac on its enhancer in tumor tissues." (PMID 38012744, 2023). "In light of the functional significance of CBX8 in inducing malignancy in multiple cancer types, it has been suggested as a therapeutic target for cancer treatment and very recently its inhibitors have been developed and are being tested." (PMID 35681547, 2022). "In our study, GSEA was performed to find possible associated biological functions and signaling pathways of these three cancers with higher CBX8 expression." (PMID 35813444, 2022). "The expression of CBX1, CBX2, CBX5, and CBX8 significantly positively correlates with cancer stemness in LIHC, LUAD, and UCEC tumors, while CBX6—negatively associates with cancer stemness in LUAD and PAAD tumors." (PMID 36361869, 2022). "CBX8 has been shown to induce cancer stemness and chemoresistance in CRC through activation of the transcription of LGR5 in a noncanonical manner." (PMID 35681547, 2022). "In LIHC, KIRC, and OV cancers, CBX8 amplification indicated relatively high change frequency, contributing to upregulating CBX8 expression." (PMID 35813444, 2022). "The CBX8 gene is highly expressed in 30 types of malignant tumors, including HNSCC, and expressed at low levels in 4 types of tumors." (PMID 35814427, 2022). "TCGA and CPTAC databases were used to compare the data between cancer and matched normal tissues on RNA and protein expression profiles and their relevant clinical information to determine the relationship between CBX8 and clinicopathological features." (PMID 35813444, 2022). "According to the transcriptomic data of TCGA, the expression of CBX8 mRNA in LSCC was significantly higher than that in para-cancer tissues by using the “limma” package (P<0.001)." (PMID 35814427, 2022). "Meanwhile, cancer tissues of 30 LSCC patients who underwent total laryngeal surgery in Shengjing Hospital affiliated with China Medical University and their paired para-cancer tissues were collected to detect the expression of CBX8 mRNA by qRT–PCR." (PMID 35814427, 2022). "Chromobox homolog 8 (CBX8) plays an important role in the occurrence and development of various tumors, and is closely related to the prognosis of patients with cancer." (PMID 34449496, 2021). "Similar to our findings, METTL3-induced m6A modification was involved in the upregulation of CBX8, which contributed to increased cancer stemness and decreased chemosensitivity in CC." (PMID 34544413, 2021). "In recent years, studies have shown that CBX8 expression imbalance is closely related to the occurrence, development, treatment, and prognosis of malignant tumors." (PMID 34449496, 2021).
cancer (continued). "Recent studies show that CBX8 promotes tumorigenesis in several cancers, including BRCA, HCC, and CRC." (PMID 33344640, 2020). "To explore the expression pattern of CBX8 in cancer, we performed a literature search on The Cancer Genome Atlas database and compared CBX8 expression levels between tumor tissues and normal tissues." (PMID 33251331, 2020). "Growing research has shown the cell proliferation promoting effects of CBX8 in different types of cancers." (PMID 31495785, 2019). "Existing evidences showed that CBX8 could regulate cell cycle progression, senescence, and differentiation in a variety of cancer types." (PMID 35210369, 2022). "The expression of CBX8 is closely related to the progression of a variety of cancers." (PMID 35814427, 2022). "CBX8 regulates cell differentiation, aging, and cell cycle progression in many malignant tumors." (PMID 35813444, 2022). "CBX8, as an oncogene, plays a role in developing these cancers we mentioned." (PMID 35813444, 2022). "In this study, through the analysis of TCGA database, we can clearly see that CBX8 is highly expressed in a large number of common malignant tumors, including HNSCC, so we speculate that CBX8 may also be involved in the progression of LSCC." (PMID 35814427, 2022). "Likewise, remarkably higher expression of CBX8 was also observed in HCC tissues, which was significantly linked to cancer stages and tumor grades." (PMID 35464847, 2022). "For instance, in many cancers CBX2/CBX8 are oncogenic while CBX6/CBX7 are tumor suppressive." (PMID 34617019, 2021). "CBX8 has a function through various pathways in different cancers." (PMID 33251331, 2020). "In one type of cancer, CBX8 may even have a function of promoting proliferation and inhibiting metastasis." (PMID 33251331, 2020). "Here, we show that CBX8 is overexpressed in many cancers compared with normal tissues." (PMID 33251331, 2020). "Overexpression of CBX8 can promote cancer cell invasion and migration, leading to metastasis." (PMID 33251331, 2020). "Dysregulation of CBX8 has been reported in various human cancers." (PMID 31495785, 2019). "Interestingly, two polycomb-group genes, i.e., CBX4 and CBX8, are among the genes that show significant up-regulation and hypermethylation in many cancer types." (PMID 27876760, 2016). "CBX8 could have different mechanisms in different cancer types, as CBX7 also plays diverse roles in different cancers." (PMID 25360999, 2014). "CBX8 could be a potential diagnostic and prognostic biomarker for LIHC, KIRC, and OV cancers." (PMID 35813444, 2022). "However, CBX8 was overexpressed in most cancers compared with corresponding normal tissues." (PMID 33251331, 2020). "Therefore, we hypothesized that miR-375 might regulate the sensitive and dynamic equilibrium of CBX7 and CBX8 expression, which is known to impact transcriptional programs in development and cancer." (PMID 27449098, 2016). "We also observed that several CBX members are frequently amplified in cancer tissues, especially CBX1, CBX2, CBX3, CBX4, and CBX8 in LUAD and LIHC tumors." (PMID 36361869, 2022). "The investigation assessed the CBX8 expression correlation with TMB, MSI, and purity in LIHC, KIRC, and OV cancers." (PMID 35813444, 2022). "CBX8, BMI1, and RNF2 are interaction proteins that maintain transcriptional repression of hundreds of cancer growth and signaling-related genes." (PMID 35813444, 2022). "A transcriptional repressor chromobox protein homolog 8 (CBX8) can directly bind to the WNK2 promotor and repress its activity in human cancers." (PMID 36123332, 2022). "Nevertheless, CBX8 has been demonstrated to induce tumor growth or progression in CRC and other cancers, and our supplementary experiment indicated that its overexpression induced the protein level of c-MYC." (PMID 35681547, 2022). "Chromobox protein homolog 8 (CBX8), a transcriptional repressor, participates in many biological processes in various carcinomas." (PMID 35813444, 2022).
cancer (continued). "CBX paralogs are frequently misregulated in cancer, with CBX2 and CBX8 as the most commonly upregulated paralogs, and CBX7 and CBX6 as the most commonly downregulated." (PMID 34617019, 2021). "Not only in HCC, but CBX8 expression was increased in pan-cancer as compared with the corresponding non-tumor tissues." (PMID 31495785, 2019). "Likewise, in the present study, significantly higher mRNA and protein expression of CBX8 were also found in HCC tissues, mRNA expression of CBX8 was remarkably correlated with patients’ individual cancer stages and tumor grades." (PMID 30481161, 2018). "Mechanism studies elucidated that METTL3 could increase CBX8 mRNA stability dependent on IGF2BP1, and then CBX8 promotes the transcription of leucine rich repeat containing G protein-coupled receptor 5 (LGR5) to maintain cancer stemness and chemoresistance." (PMID 36810281, 2023). "The four histone modification-related genes highlighted, including DPY30, CBX8, CENPT, and PADI1, have been reported to have the potential to regulate the occurrence and development of cancer to some extent by altering the histone modification of cancer-related genes." (PMID 34090418, 2021). "While many cancer-specific alterations in PcG subunits are related to specific developmental pathways or cancer-specific phenotypes, some sets of paralogs are universally up and downregulated across multiple cancers, including EZH2/EZH1, RING1B/RING1A and (CBX2/CBX8)/(CBX6/CBX7)." (PMID 34617019, 2021). "Interestingly, in Normal tissues from 18 non-cancer patients, we found that transcription of Cbx7 was positively correlated with those of Ring1, Bmi1, Mel18, and Phc2, but not with those of Cbx8 and Ezh2 (Ps<0.01)." (PMID 21060834, 2010). "Furthermore, IHC revealed that CBX8 is mainly expressed in the tumor nucleus and cytoplasm, and its expression in LSCC was significantly higher than that in paracancer tissues, positive rate in cancer tissues and paracancer tissues were respectively 67.5%(27/40)and 22.5% (9/40)." (PMID 35814427, 2022).
tumor (33 papers, 2013 to 2026). "We demonstrated that CBX8 deficiency suppresses colorectal tumorigenesis and promotes tumor cell senescence in both in vivo and in vitro models." (PMID 41943835, 2026). "MRNA expressions of CBX1, CBX2, CBX3, CBX4, and CBX8 were significantly associated with tumor grades." (PMID 35464847, 2022). "These correlations suggested that tumor CBX8 gene level is associated with better prognosis in CRC patients." (PMID 35681547, 2022). "On the other hand, tumor CBX8 gene level was associated with post-operative LMR (R = 0.479, p = 0.0001), which indicated a better prognosis." (PMID 35681547, 2022). "Hematoxylin and eosin (H&E) staining showed that both the tumor number and the area of the tumor locus were increased in association with CBX8 upregulation." (PMID 33251331, 2020). "In HCC cells, we found that enforced overexpression of CBX8 induces epithelial–mesenchymal transition, invasive migration, and stem cell-like traits, which are associated with increased tumor growth and metastasis in mice." (PMID 30718464, 2019). "We also assessed the correlation between CBX8 expression and ploidy, linked to tumor heterogeneity." (PMID 35813444, 2022). "Furthermore, the NAT CBX8 gene level is closely associated with clinicopathological parameters related to tumor progression and metastasis." (PMID 35681547, 2022). "However, it has also been revealed that CBX8 is associated with tumor-infiltration immune cells and may affect tumor recurrence and progression." (PMID 35813444, 2022). "CBX8 promotes tumor growth by maintaining a stem cell-like gene expression profile in BC cells, primarily through activation of the Notch signaling pathway, which is crucial for mammary development and tumorigenesis." (PMID 40175347, 2025). "CBX8 promotes tumor growth and metastasis capacity of lung adenocarcinoma cell lines and mouse models through the transcriptional repression of genes such as CDKN2C and SCEL, which are involved in cell cycle regulation and cellular adhesion." (PMID 40175347, 2025). "A significant dysregulation was observed for CBX3, CBX4, and CBX8, all of which were upregulated in tumor tissues." (PMID 40806514, 2025). "Taken together, these data suggested that the mRNA overexpression of CBX1, CBX3, and CBX8 were significantly related to tumor grades and patients’ tumor nodal metastasis status." (PMID 35464847, 2022). "Our findings indicated that CBX1 and CBX8 mRNAs were significantly upregulated in HCC tumor, relative to adjacent normal, tissues." (PMID 35677563, 2022). "GSEA was performed to find possible biological functions of high CBX8 protein expression of these three tumors, as follows: the cell cycle, DNA replication, linoleic acid metabolism, Wnt signaling pathway, and other tumor signaling pathways." (PMID 35813444, 2022). "We observed significant positive correlation between a high CBX1, CBX2, CBX3, CBX5, and CBX8 expression and higher tumor grade in LIHC and UCEC tumors." (PMID 36361869, 2022). "Previous studies demonstrated that CBX8 is overexpressed in CRC and it functionally induces CRC cell proliferation and inhibits tumor apoptosis, suggesting that CBX8 plays an oncogenic role in CRC." (PMID 35681547, 2022). "We divided the expression level of CBX8 in 111 TCGA tumor samples into high expression and low expression groups according to the median(6.690479164)." (PMID 35814427, 2022). "Otherwise, in the pRCC subtype, CBX2, CBX3, CBX7, and CBX8 were deregulated, and CBX2, CBX6, and CBX7 were associated with the tumor stage." (PMID 36292141, 2022). "We used GEPIA to compare expression levels of CBX mRNAs between HCC (n = 369) with normal adjacent liver (n = 160) tissues and found that CBX1 and CBX8 were significantly upregulated in tumor, relative to normal tissues." (PMID 35677563, 2022).
tumor (continued). "On the other hand, the tumor CBX8 gene and protein level demonstrated a rather opposite pattern in its prognostic significance." (PMID 35681547, 2022). "In vitro study had shown that the high expression of CBX8 facilitated tumor proliferation and metastasis by stimulating the AKT/β-catenin pathway." (PMID 35464847, 2022). "The mRNA expression of CBX1, CBX2, CBX3, CBX4, and CBX8 tended to be elevated as the tumor grade increased." (PMID 35464847, 2022). "For KIRC patients, CBX8 protein overexpression was found in tumor tissues compared with the glomeruli of normal kidney tissues." (PMID 35813444, 2022). "Immunohistochemistry outcomes implied that CBX8 was more strongly expressed in tumor tissues than in normal tissues, almost aligning with mRNA and protein expression." (PMID 35813444, 2022). "We found CBX8 enrichments in the cell cycle, DNA replications, linoleic acid metabolism, Wnt signaling pathway, and other tumor signaling pathways." (PMID 35813444, 2022). "Relevant studies have confirmed that CBX8 can induce tumor cell proliferation and migration by regulating EMT." (PMID 35814427, 2022). "In this study, immunohistochemistry was used to detect the expression of CBX8 in cervical cancer tissues and the corresponding normal tissues adjacent to the tumor." (PMID 34449496, 2021). "Taken together, these findings suggested the misregulation of CBX8 is a potential biomarker for clinical surveillance of tumor progression." (PMID 31495785, 2019). "CBX8 also significantly enhances the self-renewal and tumor-initiating capability of HCC cells, as well as properties that are essential to T-ICs." (PMID 30718464, 2019). "CBX8 protein expression also significantly correlated with tumor size, microvascular invasion, and differentiation." (PMID 30718464, 2019). "Although evidence suggests that CBX8 expression is correlated with the tumor generation and development, few studies have focused on the function and mechanism of CBX8 in HCC." (PMID 30718464, 2019). "Our results showed that CBX8 is overexpressed in HCC tissues as compared to corresponding adjacent non-tumor tissues from 3 independent cohorts." (PMID 31495785, 2019). "Functional study had showed that over-expression of CBX8 promoted tumor growth and metastasis by increasing EGR1 and miR-365-3p to stimulate the AKT/β-catenin pathway, while CBX8 inhibition suppressed these effects." (PMID 30481161, 2018). "We believe that CBX8 is a tumor suppressor in CRC considering that CRC patients with low CBX8 expression had high rate of distant metastasis." (PMID 25360999, 2014). "Both CBX7 and CBX8 have been reported to repress the INK4a/ARF tumor suppressor locus allowing normal cells to bypass senescence." (PMID 24260522, 2013). "Hence, the clinical significance of CBX8 expression in tumor and NAT of CRC patients warrants further investigation for a better understanding of its prognostic significance for CRC recurrence." (PMID 35681547, 2022). "Our study found that high expression of CBX8 was associated with unfavorable OS in ESCC, which might be attributed to its tumor promotion effect." (PMID 36140750, 2022). "Moreover, the prognostic potential of tumor CBX8 expression for the survival of CRC patients has been investigated in three studies, yet the findings were ambiguous." (PMID 35681547, 2022). "In addition, a higher tumor CBX8 gene level was correlated with lower delta-LMR (R = −0.433, p = 0.0007) and higher delta-eosinophil (R = 0.302, p = 0.0201)." (PMID 35681547, 2022). "Similarly, mRNA expressions of CBX1, CBX2, CBX3, CBX4, and CBX8 were significantly related to patients’ tumor nodal metastasis status." (PMID 35464847, 2022). "Ecotopic CBX8 production in tissues is beneficial to tumor cell growth." (PMID 34117289, 2021). "Furthermore, the effect of CBX8 knockdown on tumor growth in vivo was examined using mouse subcutaneous xenograft models." (PMID 31495785, 2019).